PDPN (podoplanin)
Diseases named in the same sentence as PDPN in open-access papers (continued):
Sharing a sentence is not in itself a finding about the gene and the disease.
melanoma (continued). "For example, lectin extracted from the seeds of the legume tree, Maackia amurensis (MASL), has an affinity for O-linked carbohydrate chains containing sialic acid and can bind to podoplanin to inhibit the growth and motility of B16 melanoma cells by inducing caspase-independent necrosis." (PMID 35163233, 2022). "Podoplanin also plays a crucial role in the progression of canine melanomas." (PMID 35163233, 2022). "Indeed, the intravenous injection of SZ168 anti-podoplanin monoclonal antibodies was found to significantly suppress pulmonary metastasis in a murine xenograft model inoculated subcutaneously with human melanoma cells." (PMID 35163233, 2022). "Anti-podoplanin monoclonal antibodies are another candidate targeted therapy for melanoma." (PMID 35163233, 2022). "Podoplanin expression is increased in metastatic human melanoma cells which have a rounded and contracted morphology; however, podoplanin knockout was found to dramatically alter the morphology of B16F10 murine melanoma cells by increasing their spread and number of protrusions." (PMID 35163233, 2022). "Although the immunomodulatory effects of CAFs are predominantly immunosuppressive and tumour-promoting, in melanoma a podoplanin (PDPN)+, FAP- CAF subtype has been shown to act in an immunostimulatory manner via development of tumour-associated tertiary lymphoid structures (TA-TLS)." (PMID 36313650, 2022). "Moreover, the siRNA-mediated knockdown of podoplanin in canine melanoma cells significantly reduced their migration and invasion capacities." (PMID 35163233, 2022). "PMab-38, an anti-dog PDPN (dPDPN) mAb, reacts with dPDPN-expressing canine melanomas and SCCs." (PMID 35159384, 2022). "The role of podoplanin in skin malignancies has been widely evaluated in melanomas and SCCs, because many cell lines are commercially available and animal models have been established; however, its role in other malignancies has been poorly evaluated, because of the lack of cell lines." (PMID 35163233, 2022). "To quantify the expression of GPR182 on lymphatics we measured mean fluorescent intensity (MFI) of GPR182 on PDPN+ lymphatic vessels; we observed a marked increase in GPR182 expression in melanoma-associated lymphatic vessels compared to lymphatics in adjacent normal skin." (PMID 35013216, 2022). "Furthermore, anti-PDPN antibodies, which neutralize PDPN–platelet interaction, suppress the tumor growth and pulmonary metastasis of human melanoma and mesothelioma in a mouse model." (PMID 32380790, 2020). "Given the recent previous preclinical mouse studies showing that anti-canine PDPN antibodies can block the growth of melanomas, our findings raise the possibility that similar types of therapies may have utility for treating canine HSA." (PMID 32571313, 2020). "Our results indicate that SZ168 may be a promising antibody to be developed as targeted therapy for PDPN-expressing malignant melanoma." (PMID 31208371, 2019). "As expected, PDPN expression was evident in melanoma cells of tumors in vivo." (PMID 22844530, 2012). "Also quite early, podoplanin has been described as a platelet aggregating factor in murine and human colon carcinoma and murine melanoma." (PMID 17343736, 2007). "Together, our integrated transcriptomic and proteomic analyses support a mechanistic model in which PDPN activates Wnt/β-catenin signaling, leading to transcriptional upregulation of PD-L1 and contributing to the formation of an immunosuppressive microenvironment in melanoma." (PMID 41573582, 2025). "However, the role of PDPN-mediated signal activation in the progression of melanoma is still unknown." (PMID 38167452, 2024). "Therefore, using phage display to screen PDPN antagonist peptide may be a promising way to find novel therapeutics for melanoma targeted therapy." (PMID 38167452, 2024).
melanoma (continued). "Treatment with the PDPN antagonistic peptide CY12-RP2 could not only inhibit the melanoma growth and metastasis both in vitro and in vivo through Wnt/β-catenin pathway blockade, but also abrogate the immunosuppressive effects of PDPN through modulating immune cells." (PMID 38167452, 2024). "Thus, targeted therapy with anti-podoplanin antibodies has therapeutic potential against melanoma." (PMID 35163233, 2022). "Although oral melanoma is classified as mucosal-type melanoma and is different from cutaneous type melanoma, PDPN was frequently expressed in both canine oral MM and human cutaneous MM, which might indicate a similarity in the mechanism for aberrant PDPN expression in these MMs." (PMID 32380790, 2020). "As Pdpn deletion in T-cells has recently been shown to significantly delay melanoma growth due to PDPN's newly discovered role as co-inhibitory receptor, we tested whether the application of the Csfr1-Cre line resulted in the undesired deletion of Pdpn in T-lymphocytes." (PMID 30972297, 2019). "However while PDPN served as the model target of this investigation, other receptors with α2,3-sialic acid residues are increased in melanoma and a variety of other cancers, and may also be targeted to some extent by MASL." (PMID 22844530, 2012). "TTo directly evaluate the immunomodulatory role of PDPN, the inhibitory peptide CY12-RP2 was tested in melanoma xenograft models using both immunodeficient BALB/c nude mice and immunocompetent C57BL/6 mice." (PMID 41573582, 2025). "Our results demonstrate that the podoplanin-CLEC-2 interaction activates platelets and promotes the aggregation of platelets and melanoma cells." (PMID 38561690, 2024). "Murine melanoma B16-F0 cells, which have two populations that express podoplanin, were sorted by FACS with anti-podoplanin staining to obtain purified PDPN + and PDPN- B16-F0 cells." (PMID 38561690, 2024). "Moreover, CY12-RP2 could inhibit melanoma lung metastasis, and abrogated the immunosuppressive effects of PDPN by increasing the proportion of CD3 + CD4 + T cells, CD3 + CD8 + T cells, CD49b + Granzyme B + NK cells, and CD11b + CD86 + M1-like macrophages and the levels of IL-1β, TNF-α, and IFN-γ." (PMID 38167452, 2024). "Tumour cell-induced platelet aggregation mediated by the interaction between PDPN and CLEC-2 is a key factor in melanoma pulmonary metastasis." (PMID 38561690, 2024). "We then examined the mRNA and protein expression levels of PDPN in melanoma cell lines (A375, A875, SK-MEL-28) by real-time RT-PCR and western blot, and found that PDPN was expressed variably in different melanoma cell lines." (PMID 38167452, 2024). "Podoplanin, a transmembrane protein that binds to the CLEC-2 receptor, is upregulated in melanoma cells, and this interaction has been shown to boost platelet-tumor cell aggregation, aiding tumor cell survival and metastasis." (PMID 39695652, 2024). "From the in vitro platelet and tumour cell aggregation assay, we found that the podoplanin-CLEC-2 interaction promoted the aggregation of platelets and melanoma cells." (PMID 38561690, 2024). "Antibody-mediated inhibition of the interaction between tumor PDPN and platelet CLEC-2 blocked the growth and pulmonary metastasis of human malignant melanoma." (PMID 38067218, 2023). "Costaining of serial sections for GPR182 and podoplanin (PDPN), a specific marker for LECs, identified that GPR182 was exclusively expressed on PDPN+ lymphatic vessels in human melanoma." (PMID 35013216, 2022). "In this study, we show a correlation between high CD147 expression levels and the number of lymphatic vessels expressing LYVE-1, Podoplanin, and VEGFR-3 in human melanoma lymph nodes." (PMID 34638342, 2021). "PDPN neutralization significantly inhibited TCIPA occurrence, tumor growth, and metastasis in nude mice injected with human melanoma or lung cancer cell lines." (PMID 34987523, 2021).
melanoma (continued). "SZ168 blocks growth and pulmonary metastasis of human malignant melanoma by inhibiting the interaction between tumor PDPN and platelet CLEC-2 and therefore is a promising antibody for therapeutic development against malignant melanoma." (PMID 31208371, 2019). "However, PDPN staining seen in our patient samples may have been due to cancer associated fibroblasts (CAFs), which would not be distinguished from actual melanoma cells by Western blotting." (PMID 22844530, 2012). "We examined cell lines and clinical specimens to further investigate PDPN expression and MASL sensitivity in human melanoma cells." (PMID 22844530, 2012). "While PDPN has been identified as an activator of the Wnt/β-catenin pathway and a stabilizer of β-catenin in melanoma, the pathways by which PDPN modulates PD-L1 have not yet been fully delineated." (PMID 41573582, 2025). "Anti-CLEC-2 monoclonal antibody 2A2B10 has been demonstrated to inhibit hematogenous metastasis and thrombosis of PDPN-positive mouse melanoma without a significant bleeding tendency." (PMID 38504248, 2024). "Conversely, this suggests that inhibition of platelet aggregation via depletion of podoplanin and CLEC-2 expression may diminish melanoma pulmonary metastasis." (PMID 38561690, 2024). "Furthermore, soluble factors released by dedifferentiated melanomas are found to promote FRC elongation, proliferation, and upregulation of the activation markers PDPN, tenascin C, fibronectin, and IL6 in vitro." (PMID 38038708, 2024). "Nevertheless, the mechanism between PDPN and melanoma is still not clear and needs further elucidation." (PMID 38167452, 2024). "Blocking the PDPN + LNSCs by LTbR-Ig could increase the infiltration and proliferation of CD4 + TILs and inhibit melanoma development." (PMID 38167452, 2024). "In our experiment, either a lack of podoplanin on melanoma cells or CLEC-2 depletion on platelets blocked platelet aggregation and reduced melanoma pulmonary metastasis in vivo." (PMID 38561690, 2024). "Our results show that a Syk inhibitor can partially block platelet aggregation and pulmonary metastasis in vitro and in vivo, which demonstrates that the syk-dependent signalling pathway in the podoplanin-CLEC-2 interaction plays a role in platelet aggregation and melanoma pulmonary metastasis." (PMID 38561690, 2024). "Treatment with a CLEC2 inhibitor Co-HP suppressed lung metastasis of PDPN-expressing melanoma cells, but not that of PDPN-negative lung cancer cells." (PMID 34987523, 2021). "The tumour was strongly and diffusely positive for AE1/AE3, and CK7, while negative for calretinin, WT1, and D2-40 (podoplanin) (mesothelial markers); S100 protein and Melan A (melanoma markers), and CD34 (epithelioid sarcoma markers)." (PMID 32149365, 2020). "We employed siRNA to verify the effects of PDPN and MASL on melanoma cell growth and migration." (PMID 22844530, 2012). "Moreover, PDPN is expressed on hematopoietic cells, including subpopulations of T cells and macrophages, which is beneficial for CLEC-2 binding with PDPN to promote melanoma growth and metastasis through regulating immune cells." (PMID 38167452, 2024). "Moreover, these novel findings are supported by other groups that identified the upregulation of PDPN as lymphatic anchorage marker by CHI3L1 in macrophages, as well as reduction in lymphatic spreading of B16-BL6 melanoma cells upon treatment with anti-CHI3L1 antibodies." (PMID 38605414, 2024). "Furthermore, we used Ph.D.TM-12 Phage Display Peptide Library to obtain the PDPN antagonist peptide CY12-RP2, and found that CY12-RP2 could significantly inhibit the melanoma growth and metastasis both in vitro and in vivo." (PMID 38167452, 2024).
melanoma (continued). "This is in contrast to other studies which have shown the absence of LYVE-1 and podoplanin positive lymphatics in human ciliary body with melanoma without extraocular extension, although neo-lymphatic vessels can proliferate into malignant melanomas of the ciliary body with extraocular extension." (PMID 36163311, 2022). "FSCs isolated from human skin and melanoma biopsies could be readily infected with artLCMV vaccine vectors with the majority of LCMV-NP+ FSCs showing co-expression of CD90 (Thy1) and PDPN." (PMID 34354077, 2021). "We could not detect podoplanin-positive ECs (lymphatic TuECs) in suspensions of melanoma lesions, although this population made up 40–60% of total ECs in normal skin." (PMID 21179030, 2011). "An immunofluorescence study was performed to evaluate the expression of the three main lymphangiogenesis markers, Podoplanin, LYVE-1 and VEGFR-3, on 16 resected human melanoma lymph node metastases harboring high or low CD147 expression." (PMID 34638342, 2021).
mesothelioma (45 papers, 2006 to 2026). A usually malignant and aggressive neoplasm of the mesothelium which is often associated with exposure to asbestos. "Besides, Podoplanin (PDPN) is a mucin-like glycoprotein whose overexpression has been associated with mesothelioma, EC, LCa, and mesenchymal GBM." (PMID 36261831, 2022). "Altered expression of podoplanin is associated with mesothelioma, squamous cell carcinoma of oral mucosa, and germ cell tumors, suggesting that podoplanin may influence invasive and proliferative activity." (PMID 21773035, 2011). "The pathology report from the right pleural frozen sections and pleural exudate showed findings consistent with advanced-stage mesothelioma positive for calretinin, podoplanin (D2-40), and CK5/6." (PMID 39445262, 2024). "Next, the 90Y-labeled anti-PDPN antibody NZ-12 was reported to inhibit tumor growth in mesothelioma NCI-H226 xenograft-bearing mice." (PMID 35159384, 2022). "NZ-16 has a higher affinity and showed higher tumor uptake in a PDPN-expressing H226 mesothelioma mouse model than NZ-12." (PMID 34685483, 2021). "A previous study reported that 90Y-labeled anti-PDPN antibody NZ-12 suppresses tumor growth in a mesothelioma model cell line NCI-H226 (H226); unfortunately, complete remission was not achieved." (PMID 34685483, 2021). "Podoplanin is a well-known diagnostic marker of MPM, as mesothelioma cells show high expression of podoplanis whereas the specific function has yet to be determined." (PMID 32260559, 2020). "In previous studies, we employed an antibody (clone E-1) against podoplanin that was strongly expressed on mesothelioma cells." (PMID 32260559, 2020). "The results showed that 5B3 mAb has an exceptional specificity for recognizing PDPN, especially in sections from lung tissue, mesothelioma, seminoma and submucosal lymphatic vessels." (PMID 29976954, 2018). "NCI-H226 cells were incubated with JMAM mAbs followed by staining with existing Abs already known to bind to mesothelioma [anti-calretinin, anti-podoplanin (D2-40), anti-GLUT-1, anti-CD25 (BC96), anti-CD26 (1F7, 5F8), anti-C-ERC/mesothelin (22A31)]." (PMID 27342200, 2016). "This is consistent with the expression pattern of podoplanin found to be upregulated in mesothelioma and other human cancers." (PMID 26689993, 2016). "The diagnosis of malignant mesothelioma in humans can be supported by staining for proteins commonly expressed in mesotheliomas, including calretinin, cytokeratins, mesothelin, WT-1 and podoplanin (D2-40)." (PMID 24405760, 2014). "The epithelia of biphasic mesotheliomas show strong reactivity for Cytokeratin 8/18, whereas Podoplanin is the most recently recognized marker for epithelioid mesotheliomas." (PMID 16704740, 2006). "However, this issue can be easily overcome by a simple strategy proposed by researchers: the screening of other mesothelioma-specific markers, such as podoplanin, cytokeratin, or mesothelin, which can help to differentiate lung carcinoma from mesothelioma." (PMID 38928369, 2024). "Another mesothelial marker, podoplanin (D2‐40), is commonly co‐expressed with MSLN in mesothelioma, has an association with improved prognosis and may have an inverse relationship with atypia." (PMID 37040900, 2023). "PDPN expression has been reported in many cancers, including squamous cell carcinomas (head and neck, lung, uterine, oral, and esophageal carcinomas), malignant gliomas, mesotheliomas, bladder cancers, osteosarcoma, ovarian cancer, and testicular tumors." (PMID 35159384, 2022). "Third, the present study employed only one PDPN-expressing mesothelioma cell line." (PMID 34685483, 2021). "Flow cytometry using LpMab‐21 detected endogenous expression of PDPN by the human cancer cell lines as follows: mesothelioma, NCI‐H226; oral squamous cell carcinoma, HSC‐2 and HSC‐4; squamous cell carcinoma of the lung, PC‐10; and human osteosarcoma, U‐2 OS and MG‐63." (PMID 28101903, 2017).
mesothelioma (continued). "Podoplanin, which is a member of a type-1 transmembrane sialomucin-like glycoprotein family, serves as a marker of lymphatic endothelial cells but is also expressed by mesothelioma." (PMID 26064894, 2015). "All presumptive sarcomatous mesotheliomas stained positively for podoplanin and vimentin." (PMID 24405760, 2014). "In a series of 30 mesotheliomas with epitheloid growth pattern, 93% expressed podoplanin." (PMID 17179989, 2007). "Similarly, although podoplanin has been presented as an interesting immunohistochemical marker in the diagnosis of mesothelioma, its expression is frequent in the epithelioid subtype but usually absent in the sarcomatoid subtype, in agreement with our findings on PNsarc cell lines." (PMID 27129173, 2016). "By flow cytometry, chLpMab‐2 detected endogenous PDPN in human cancer cell lines such as PC‐10 of lung squamous cell carcinoma and NCI‐H226 of mesothelioma." (PMID 28332312, 2017). "Antibodies against Podoplanin, Mesothelin, EMA, and GLUT-1 stained cell-block specimens, which confirmed these atypical cells as derived from mesothelioma." (PMID 27342200, 2016). "In order to find an explanation why GAS5 expression should be high in tumor cells, we compared GAS5 expression to known mesothelioma markers and found that GAS5 expression was positively correlated to podoplanin expression." (PMID 24885398, 2014). "Epithelioid-type MPMs were immunostained with antibodies against intelectin-1 or typical mesothelioma markers, such as calretinin, CK5/6, podoplanin, WT-1, and mesothelin." (PMID 22768319, 2012). "Podoplanin is a mucin-like glycoprotein that pathologists commonly use to differentiate mesothelioma from bronchogenic cancer in females with no smoking history." (PMID 39445262, 2024). "IHC staining of mesothelioma related markers including BAP1, EMA, Thrombomodulin (CD141), WT1, Podoplanin (D2-40), Calretinin and Cytokeratin6 (CK-6) revealed increased protein expression in 2175, 1187 or 1157 3D spheroids when compared to their 2D counterparts." (PMID 36091141, 2022). "Unfortunately, another mesothelioma cell line with high PDPN expression is not available." (PMID 34685483, 2021).